SETBP1 (SET binding protein 1)
Diseases named in the same sentence as SETBP1 in open-access papers (continued):
Sharing a sentence is not in itself a finding about the gene and the disease.
cancer (continued). "The degron is therefore more affected by somatic SETBP1 mutations that promote cancer than by germline mutations that cause SGS, implying that the threshold for cancer caused by mutations in the SETBP1 degron is higher than that for prenatal developmental alterations in SGS." (PMID 29861492, 2018). "As SETBP1 mutations are also seen in other cancer types, like tumors arising in children with SGS, understanding the role of SETBP1 in hematopoietic neoplasms will contribute to a better understanding of the oncogenic mechanism of other tumors and so to establishing an adequate treatment strategy." (PMID 28881700, 2017). "It is now evident that the SETBP1 mutation can be an important factor in cancer development, progression and maybe resistance." (PMID 28881700, 2017). "Furthermore, the similarities observed in the molecular consequences of germline and somatic SETBP1 mutations support the rationale behind recent studies which have elegantly repurposed drugs used in cancer therapy for the treatment of developmental disorders in mouse models." (PMID 28346496, 2017). "We gave a new view on the mental retardation of SETBP1-HD and performed a pan-cancer analysis of SETBP1 gene in different tumors for the first time." (PMID 37150818, 2023). "Regulator of Hoxa9, a gene involved in cancer persistence with respect to Setbp1‐mediated myeloid progenitor self‐renewal." (PMID 37872881, 2023). "In some of these cancers, elevated SETBP1 expression appears to cooperate with FLT3‐ITD to trigger AML development." (PMID 37489294, 2023). "Elevated SETBP1 expression at high cell densities is a common phenomenon observed in many normal and cancer cell lines." (PMID 37489294, 2023). "A pan-cancer analysis of SETBP1 was conducted based on previous reported data sets for the first time." (PMID 37150818, 2023). "SETBP1 expression has been extensively studied in various diseases, including cancers, where it is abnormal compared with normal tissues." (PMID 35898891, 2022). "Two GRBC-prioritized missense variants, SETBP1:c.4129G > C and C7orf34:c.248C > T, were present in FBRCAX and were also enriched in cancer patients from both NFE-TCGA and EUR-UKB." (PMID 31681433, 2019). "However, SETBP1 targets with previously reported functions involving cancer and DNA damage had variable TF activity in the blood." (PMID 38165902, 2024). "We performed a pan-cancer analysis of SETBP1 gene in different cancers for the first time." (PMID 37150818, 2023). "In cancers, familiar biological functions for SETBP1 are related to DNA replication." (PMID 37535001, 2023). "Mutations in the SKI region contribute to cancer malignancy by stabilizing the SETBP1 protein; on the other hand, increased SETBP1 protein not caused by mutations has also been reported." (PMID 37489294, 2023).
cancer (continued). "Third, only two cancer types were employed in assessing the immunotherapeutic efficacy of SETBP1 mutations, no additional cancers with both mutational profiles and ICI treatment information were acquired." (PMID 37535001, 2023). "It has been shown that SETBP1 is highly expressed in some cancers, driving carcinogenesis." (PMID 35898891, 2022). "The overexpression of miR211 inhibited the expression of SETBP1 significantly and the restoration of SETBP1 expression also could reverse the inhibitory effect of miR211 on cancer cell proliferation as well as metastasis." (PMID 31333725, 2019). "To compare the intensity of effect of mutations in the group of individuals who developed cancer versus those who did not, we calculated the median SETBP1-βTrCP1 interaction ΔΔG value for each group based on results from in silico protein modeling." (PMID 28346496, 2017). "Additionally, this suggests that the functional threshold for the development of cancer driven by the disruption of the SETBP1 degron is higher than for the alteration in prenatal development in SGS." (PMID 28346496, 2017). "The parallelisms between the functional consequences of germline and somatic SETBP1 mutations is relevant for the better understanding of SGS but could also deliver insight into the role of SETBP1 as a cancer driver." (PMID 28346496, 2017). "Despite this decrease however, SETBP1 score never fell below the OncoScore cut-off threshold, therefore remaining in the cancer-associated genes group." (PMID 28387367, 2017). "However, to our knowledge, the clinical significance of SETBP1 mutations in cancer ICI treatments has not been elucidated." (PMID 37535001, 2023). "Therefore, changes in nutritional status associated with increased cell density and decreased blood flow in cancer tissues may contribute to increased SETBP1 expression." (PMID 37489294, 2023). "Therefore, the role of SETBP1 in cancer remains controversial and in GC remains obscure." (PMID 35898891, 2022). "However, SETBP1 appears to play a dual role in different cancer types." (PMID 35898891, 2022). "The group of individuals who developed cancer carry SETBP1 mutations which are more disruptive to the interaction of SETBP1 with βTrCP1 than the group of patients who did not develop cancer (βTrCP1 interaction ΔΔG = 3.57 vs 0.65, p = 0.029, Mann-Whitney U test)." (PMID 28346496, 2017). "This dual role in cancer and development is not unique to SETBP1; a growing number of genes in which germline mutations cause developmental disorders, such as HRAS, ASXL1, EZH2 and FGFR2, are also known to harbor overlapping somatic mutations which drive the development of cancer." (PMID 28346496, 2017). "While we used NEO1 as an example, several other genes known to have roles in cancer proliferation and various pathway cascades were identified within these shared compartments, including EPS8, FAM92A, IRS1, and SETBP1." (PMID 37016431, 2023). "SET binding protein 1 (SETBP1) plays crucial roles in various biological processes; however, its involvement in cancer immune checkpoint inhibitor (ICI) treatments has never been studied." (PMID 37535001, 2023). "By re-sequencing SETBP1 in samples with ACML and other common human cancers, they found that around 25% of the ACML patients tested positive for SETBP1, while most of the other types of tumors were negative." (PMID 25299648, 2014).
hematological malignancies (11 papers, 2015 to 2025). "Studies have shown that somatic SETBP1 mutations causing hematologic malignancies had greater driving effect to the degron than germline SETBP1 mutations leading to SGS." (PMID 37150818, 2023). "Many studies have shown that somatic SETBP1 mutations were associated with hematologic malignancies." (PMID 37150818, 2023). "The discovery of somatic mutation associated with hematological diseases and the advent of Next-Gen sequencing studies paved the way to unveiling many missense mutations within the SETBP1 gene." (PMID 28881700, 2017). "Apart from mutations in CSF3R and SRSF2, mutations in SETBP1 has also been demonstrated in hematological malignancies." (PMID 28209919, 2017). "The association of SETBP1 activation with poor prognosis in many hematological diseases suggests that the identification of specific therapeutic strategies for these patients may provide an advantage, increasing the cure rate and survivals." (PMID 28881700, 2017). "Interestingly, not only SETBP1 overexpression but also SETBP1 mutations have been associated with hematological disorders." (PMID 25763353, 2015). "Among the 11 novel or very rare SETBP1 variants we identified, two truncating variants resulted to be de novo, and two likely pathogenic missense, previously reported as somatic SETBP1 variants in hematological malignancies, which we found to be inherited from reportedly asymptomatic parents." (PMID 33391157, 2020). "The most significantly hypermethylated CpGs were frequently linked to genes involved in the pathogenesis of hematological diseases, including RUNX1, BRD4, SRSF2, SETBP1 and TNFSF10." (PMID 40319310, 2025). "De novo missense germinal variants of SETBP1 in a 12 base pair hotspot of exon 4, encoding SETBP1 protein residues 868–871, cause both Schinzel–Giedion syndrome (SGS) and hematological malignancies." (PMID 33337535, 2021). "Mutations in SETBP1, by contrast, were found in CNL, CMML but also other hematological malignancies, making it a rather poor isolated prognostic marker for hematological diseases." (PMID 28209919, 2017).
neurodevelopmental disorder (11 papers, 2019 to 2026). A behavioral and cognitive disorder with onset during the developmental period that involves impaired or aberrant development of intellectual, motor, or social functions. "Despite a clear link between SETBP1 mutations and neurodevelopmental disorders the precise role of SETBP1 in neural development remains elusive." (PMID 39350244, 2024). "Rare de novo heterozygous loss-of-function SETBP1 variants lead to a neurodevelopmental disorder characterized by speech deficits, indicating a potential involvement of SETBP1 in human speech." (PMID 39580495, 2024). "Despite the association of SETBP1 with neurodevelopmental disorders, little is known about its role in brain development." (PMID 36805818, 2023). "Several genes directly targeted by SETBP1 or associated with neurodevelopmental disorders (NDDs) have been identified as aberrant genes in patient." (PMID 36161179, 2022). "While there is a clear association between mutations in SETBP1 and neurodevelopmental disorders, the role of SETBP1 in brain development is largely unknown." (PMID 39350244, 2024). "Interestingly, different types of germline genetic disruption in the SETBP1 gene cause clinically distinct neurodevelopmental disorders with a broad and variable clinical spectrum." (PMID 39580495, 2024). "Despite its clear association with several neurodevelopmental disorders, the function of SETBP1 in the developing brain remains unknown." (PMID 36805818, 2023). "SETBP1 gene is located at 18q12.3 and is associated with several neurodevelopmental disorders." (PMID 36805818, 2023). "Given the important role of SETBP1 in this developmental window, genetic variation in this gene may lead to neurodevelopmental disorders." (PMID 41282480, 2025). "Interestingly, four of these LoF variants disrupted genes previously implicated in neurodevelopmental disorders: KAT6A (c.1599-56_1621del in proband 10), SETBP1 (c.1781del, p.P594Lfs*36 in proband 13), TNRC6B (c.2040G>A, p.W680* in proband 15) and ZFHX4 (c.3646-1G>A in proband 14)." (PMID 29463886, 2019). "His clinical and facial features widely overlap with typical SETBP1-HD presentation, although we cannot exclude that the haploinsufficiency of some of the genes involved in the rearrangements may also have a contributing role in the patient’s phenotype and neurodevelopmental disorder." (PMID 38520002, 2024). "In contrast, heterozygous de novo germline loss-of-function (LoF) variants (truncating and SETBP1-specific microdeletions) lead to SETBP1-haploinsufficiency disorder (MIM #616078, OMIM 606078) which is a milder neurodevelopmental disorder showing a broad range of symptoms with variable severity." (PMID 39580495, 2024). "A significant number of these genes (CHD3, SETD1A, KAT6A, SETBP1, TNRC6B, ZFHX4, ARID1A and TRIO) have been associated with neurodevelopmental disorders with or without speech problems." (PMID 29463886, 2019).
nervous system disorder (3 papers, 2020 to 2024). A non-neoplastic or neoplastic disorder that affects the brain, spinal cord, or peripheral nerves. "DMRs overlapping genes involved in neurological disorders were also identified, including hypomethylation of SETBP1 (−28.23%)." (PMID 32033187, 2020). "However, in the context of neurological disorders, an association between GATA2 and SETBP1 has not been reported." (PMID 39350244, 2024).
overlap syndrome (3 papers, 2017 to 2024). "In this review, we summarized the latest data on the role of SETBP1 mutations in the overlap syndrome." (PMID 29225884, 2017). "SETBP1 mutations may serve as a biomarker for the diagnosis and poor prognosis of the overlap syndrome." (PMID 29225884, 2017). "SETBP1 mutations may serve as a biomarker for the diagnosis and poor prognosis for the overlap syndrome." (PMID 29225884, 2017).
blood cancers (2 papers, 2023 to 2024). "SETBP1 (SET binding protein 1) is the causative gene for Schinzel‐Giedion syndrome, and mutations in the same region are also observed in various blood cancers." (PMID 37489294, 2023).
hematological cancers (2 papers, 2015 to 2017). "Mutations in SETBP1 have been widely reported in hematological cancers." (PMID 26169266, 2015).
SETBP1 also shares sentences with these, for which no sentence is quoted: Noonan syndrome (3 papers); triple-negative breast carcinoma (3); acute T-cell lymphoblastic leukemia (2); primary myelofibrosis (2); speech disorder (2); ankyloglossia (1); attention deficit-hyperactivity disorder (1); autism spectrum disorder (1); basal cell carcinoma (1); blast (1); breast tumor (1); Cerebellar hypoplasia (1); childhood apraxia of speech (1); chronic graft versus host disease (1); congenital megacolon (1); Cornelia de Lange syndrome 4 (1); cryptorchidism (1); duodenitis (1); Dysarthria (1); endometrium cancer (1); eosinophilia (1); Expressive language delay (1); Familial Dystonia (1); gastritis (1); germ cell tumor (1); granulocytosis (1); Hereditary Motor and Sensory Neuropathy Type 1 (1); hypospadias (1); Koolen-de Vries syndrome (1); language delay (1).
A further 29 diseases each share a sentence with SETBP1 in 1 paper.